TLR4 (toll like receptor 4)
Diseases named in the same sentence as TLR4 in open-access papers (continued):
Sharing a sentence is not in itself a finding about the gene and the disease.
kidney failure (8 papers, 2015 to 2026). An acute or chronic condition that is characterized by the inability of the kidneys to adequately filter the blood. "TLR4 mRNA expression was found to be significant in diabetic patients with kidney failure when compared with patients with either DM or kidney failure." (PMID 33442388, 2020). "These implicate that the disorder of cell cycle and immune system may play pivotal signaling roles, with the interlinks between ACTB and TLR4 potentially driving the common pathogenesis in both heart and kidney failure." (PMID 39351221, 2024). "Overall, TLR4 status did not predict kidney failure-free survival; however, among patients with IFTA < 50% (n = 63), moderate-to-severe tubular TLR4 expression was associated with worse survival than negative-to-mild expression (p = 0.021)." (PMID 41874883, 2026). "The expressions of TLR2 and TLR4 remarkably increased in nephrotic diabetic patients with or without kidney failure and in non-diabetic nephrotic patients (with kidney failure) in comparison with normal subjects." (PMID 33442388, 2020). "The higher expression of TLR2 and TLR4 in nephrotic diabetic patients with kidney failure than in nephrotic diabetic patients without kidney failure reflects their important roles in the progress of DNP to reach the end disease state subjected to HD." (PMID 33442388, 2020). "Eight genes related to kidney toxicity, including kidney failure (CASP1, FCGR2A, FCGR2B, TLR2, TLR4, P = 0.003), damage of renal tubule (TLR2, TLR4, P = 0.01), proximal tubular toxicity (CTSS, LYZ, SLC22A5, P = 0.007) and their expression across 6 datasets were not confounded by tissue types." (PMID 28051114, 2017). "Therefore, this study was conducted to scrutinize the patterns of changes and roles of TLR2 and TLR4 expressions in relation to proinflammatory Th1 cytokine levels and INS resistance in nephrotic diabetic patients with or without kidney failure." (PMID 33442388, 2020).
liver dysfunction (8 papers, 2016 to 2025). "Given the TLR4 signaling pathway’s pivotal role in hepatopathy pathogenesis and progression, the development of pathway-specific antagonists has become a key research direction for HCC prevention and treatment." (PMID 41395459, 2025). "In studies on fructose- and ethanol-induced liver dysfunction, it was observed that the LPS content and Toll-like receptor 4 (TLR4) expression in the liver were decreased by oral intake of polyphenols." (PMID 35723314, 2022). "Specifically, toll-like receptor 4 (TLR4) was observed to be increased in the urine of patients with liver dysfunction, AKI, and inflammatory insults." (PMID 35505725, 2022). "Future studies on how to target the PTRF/TLR-4/PI3K/Akt axis and clarify its specific roles in different cell types to alleviate liver dysfunction are warranted." (PMID 37346294, 2023). "In conclusion, our study suggested that MD2 deficiency or inhibition by L6H21 can mitigate Ang II-induced liver dysfunction, pathological injury, inflammation and fibrosis, and activation of NF-κB and ERK pathways through reducing the formation of the MD2/TLR4 complex." (PMID 31861702, 2019).
lymphopenia (8 papers, 2021 to 2025). Reduction in the number of lymphocytes. "The results showed also a highly significant increase in the concentration levels of serum IL-10 (P value = 0.04*)) and serum TLR-4 (P value = 0.006*)) in patients having lymphopenia." (PMID 36864077, 2023). "IL-10 and TLR4 levels were significantly higher in patients having lymphopenia." (PMID 36864077, 2023). "Recent findings in chronic inflammatory diseases and cancer indicate that T-cell failure and lymphopenia may be related to changes in the expression level of TLR4." (PMID 34631699, 2021). "The results showed significant increases in the levels of serum IL-10 and TLR-4 in patients having lymphopenia compared to patients with normal lymphocytic count." (PMID 36864077, 2023). "Dysbiosis, disruption of the intestinal barrier, and activation of pattern‐recognition receptors such as TLR4 can trigger downstream NF‐κB and NLRP3 inflammasome signaling, fostering chronic systemic inflammation, cytokine release, and a shift toward neutrophilia with relative lymphopenia." (PMID 41466721, 2025).
mantle cell lymphoma (8 papers, 2014 to 2025). Mantle cell lymphoma is a rare form of malignant non-Hodgkin lymphoma affecting B lymphocytes in the lymph nodes in a region called the ``mantle zone''. "In chronic lymphocytic leukemia (CLL), low TLR2 expression is linked to a poor prognosis, while in mantle cell lymphoma (MCL), TLR4 signaling can trigger tumor growth." (PMID 40922674, 2025). "The induction of genes related to B cell activation and APC function was also observed in human Mino cells, a TLR4 expressing mantle cell lymphoma cell line." (PMID 32974162, 2020). "TLR4 signaling in human mantle cell lymphoma cells inhibited T cell proliferation and CTL-induced cytolysis, and this effect was partially restored by neutralization of IL-10 and/or VEGF." (PMID 28881826, 2017). "Similarly, the TLR4 positive human mantle cell lymphoma line Mino showed in vitro activation with G100 that was blocked with an anti-TLR4 antibody." (PMID 32974162, 2020). "Moreover, among several TLRs expressed by Mantle cell lymphoma (MCL) cells, TLR4 is reported among the highest-expressed molecules." (PMID 37822929, 2023). "LPS-pretreated TLR4-positive/myeloid differentiation 88 (MyD88)-positive mantle cell lymphoma(MCL) inhibited the proliferation and cytolytic activity of T cells by secreted IL-10 and VEGF, and triggers a cascade that leads to MCL growth and evasion from immune surveillance." (PMID 25299052, 2014). "In mantle cell lymphoma (MCL), TLR1, TLR4, TLR7, TLR9 and TLR10 exhibit significant mRNA levels, whereas TLR2, TLR3, TLR5 and TLR8 are negative." (PMID 25112836, 2014).
Multiple Organ Failure (8 papers, 2014 to 2025). A progressive condition usually characterized by combined failure of several organs such as the lungs, liver, kidney, along with some clotting mechanisms, usually postinjury or postoperative. "Histone levels in septic patients are significantly increased and might mediate disease aggravation by cellular injury and inflammation via TLR4 signaling, which potentially results in multiple organ failure and fatal outcome." (PMID 25260379, 2014). "Together, it might be possible that θ-toxin activates TLR4, and that the excessive activation of TLR4 by α-toxin contributes to the characteristics of C. perfringens infection, such as the destruction of muscle, shock, multiple organ failure, systemic inflammation, and death of patients." (PMID 33763386, 2021). "Indeed, as soon as a pathogen is detected by the immune system, pro‐inflammatory cytokines will be released, and, an early release of TNF‐α by macrophages (through TLR4 pathway) may induce disseminated intravascular coagulation, hypotension and multiple organ failure." (PMID 34288548, 2021).
otitis media (8 papers, 2005 to 2025). Inflammation of the anatomical structures of the middle ear, which is most often caused by an infectious process. "Other SNPs in the TLR4 region also showed indications of association with otitis media, but it is unclear what the significance of these findings are and if these constitute an independent signal or not." (PMID 26177520, 2015). "C3H/HeJ mice with a missense mutation in the Tlr4 gene have a retarded response to endotoxin and an increased susceptibility to otitis media." (PMID 22539951, 2012). "Mutations that lead to immune or autoimmune conditions can also increase susceptibility to otitis media following exposure to bacteria, such as in Tlr2, Tlr4, Myd88, Ticam1 and Fas mutants." (PMID 21936904, 2011). "It has also been reported that bacterial clearance is impaired in TLR4−/− mice compared with WT mice, indicating that TLR4 plays an important role in controlling middle ear inflammation in NTHi-induced otitis media." (PMID 34360632, 2021). "Previous candidate gene studies associated a number of immune system genes with otitis media, which included TNF-α, IL-6, IL-10, Tlr4, surfactant, CD14, FcγRIIa, IFNγ, Eya4, p73, MyD88, Fas, E2f4, Plg, Fbxo11, and Evi1." (PMID 24466073, 2014). "The increased expression of TLR2, TLR3 and TLR4 as a consequence of allergen exposure is in line with a previous report demonstrating an increase of TLR2 protein in chronic middle ear inflammation." (PMID 16146574, 2005). "On the basis of these results, the authors suggested that activation of TRIF/type I IFN responses is important in both the pathogenesis and resolution of NTHi-induced otitis media and that TLR4 may be involved in this process." (PMID 34360632, 2021). "A study that compared 53 selected SNPs in 35 genes in the blood of 624 children with otitis media and 778 patients without otitis media found that the single nucleotide polymorphism (SNP) rs5030717 in the TLR4 gene region was associated with the occurrence of otitis media." (PMID 34360632, 2021). "In vivo experiments utilizing a rat model of otitis media demonstrated a significant reduction in the levels of pro-inflammatory cytokines TNF-α, IL-1β, TLR4, and IL-6, and greater levels of Nrf-2 and SOD in comparison to untreated controls." (PMID 40143156, 2025). "A histopathological analysis confirmed that treatment with the nanocarriers reduced the levels of pro-inflammatory cytokines (IL-1β, TNF-α, TLR4, IL-6) and raised the levels of antioxidant markers (Nrf-2, SOD) in an in vivo rat model of otitis media." (PMID 40143156, 2025). "A comparison of the middle ear mucosa of non-otitis media, COM, and CSOM groups showed that mRNA and protein levels of TLR4 were not different between non-otitis media and COM groups, but were significantly decreased in the CSOM group." (PMID 34360632, 2021).
prediabetes (8 papers, 2019 to 2024). "The contribution of TLRs, specifically TLR2 and TLR4, to the development of prediabetes and diabetic sensory neuropathy has been elucidated by mitigating the inflammatory response in both human subjects and various mouse models." (PMID 38390212, 2024). "Then, LPS from the gut lumen binds Toll-like receptor 4 (TLR4) to damage the intestinal barrier, and serum LPS moderately increases, which is an inflammatory state of prediabetes." (PMID 38055342, 2024). "Long-term exposure to BPA-induced TLR4-dependent hypothalamic inflammation exacerbates diet-induced prediabetes." (PMID 37108405, 2023). "Robinson and colleagues suggest that along with changes in monocytes, neutrophil expression of TLR-4 is reduced following only 10 days of HIIT in a slightly younger cohort of individuals with prediabetes than in our study." (PMID 32431698, 2020). "Results of this study and previous results showed an overexpression of Toll-like receptors (TLR4 and 6), Janus kinase 2 (JAK2) and Vascular endothelial growth factor A (VEGFA) in prediabetes patients." (PMID 37457235, 2023).
SARS-CoV infection (8 papers, 2013 to 2022). "Studies have revealed that TLR3−/−-, TLR4−/−-, and TRIF-related adaptor molecule (TRAM)−/−- deficient mice are more vulnerable to SARS-CoV infection and show greater transient weight loss when compared to wild-type mice." (PMID 35847031, 2022). "The activation of TLR-3 and TLR-4 through TRIF adapter protein imposes strong cell-intrinsic defense response against SARS-CoV infection." (PMID 33262955, 2020). "The results obtained from their study indicate that the expression of TLR4/TLR2 is upregulated at 24 h after SARS-CoV infection, suggesting its importance in the generation of immune responses." (PMID 32616763, 2020). "We confirmed that Ticam2, a TLR adapter protein specific to TLR4,contributes to SARS-CoV pathogenesis by showing that Ticam2−/−mice have increased susceptibility to SARS-CoV infection." (PMID 28592648, 2017). "Mice lacking TRIF (the adaptor protein for TLR3 and TLR4) are more susceptible to SARS-CoV infection." (PMID 35847031, 2022). "As a proof of concept, TLR3/TLR4 double-negative mice were more susceptible to SARS-CoV infection, and the deletion of TRIF increased the SARS-CoV-dependent risk of mortality." (PMID 34576716, 2021). "This prompted the usage of TLR-3 and TLR-4 agonists to have protection against SARS-CoV infection." (PMID 33262955, 2020). "Oxidized phospholipids that accumulate in HPAI and SARS-CoV infections also likely contribute to ALI and hypercytokinemia (“cytokine storm”) by signaling though toll-like receptor 4 (TLR4) and TRIF/TICAM1 in macrophages, activating NF-kB and inducing IL6." (PMID 30486363, 2018). "Reportedly, severe acute respiratory syndrome (SARS-CoV) and mouse hepatitis virus (MHV) infection can also induce TLR4 expression, suggesting that TLR4 possibly has a similar effect both in avian and mammalian species as well as during coronavirus infection." (PMID 24168272, 2013). "While the ligand that activates TLR4 signalingfollowing SARS-CoV infection has not yet been identified, our group has recently shown thatTLR4 deficient mice are highly susceptible to SARS-CoV infection." (PMID 28592648, 2017). "Interestingly, while PTPN4 acts as an inhibitor, the TLR4 signaling pathway is activated by the SARS-CoV-2 spike protein, and mice lacking TLR4 had more severe SARS-CoV infections than wild-type mice." (PMID 34070971, 2021).
septic shock (8 papers, 2012 to 2022). Shock caused by infection; frequently caused by gram negative bacteria, although some cases have been caused by other bacteria, viruses, fungi, and protozoa; characterized by fever, chills, tachycardia, tachypnea, and hypotension. "In this regard, treatment with anti-GP, anti-TLR4 and anti-LSECtin Abs could be used to reduce the inflammatory responses caused by shed GP and may be helpful to alleviate the septic shock-like syndrome observed with EBOV infection." (PMID 26943817, 2016). "Lipopolysaccharide (LPS), a major structural component of gram negative bacteria cell walls, induces the systemic inflammation observed in septic shock by interacting with TLR-4." (PMID 22363498, 2012).
Sjögren’s syndrome (8 papers, 2013 to 2024). "However, IκBζ-deficient epithelial cells provoke a Sjögren’s syndrome-like inflammation in mice, and IκBζ-deficient hepatocytes showed defective proliferation due to impaired TLR4-signaling." (PMID 33542719, 2020). "Hanying Mei found that total glucosides of paeony can reduce the inflammatory response in mice with Sjogren’s syndrome by regulating the activity of TLR4/MyD88/NF-κB signaling pathway and play an anti-inflammatory role." (PMID 39664524, 2024). "Here, we further found that EVs from early-passage iMSCs had better immunomodulatory potency than EVs from late-passage iMSCs in TLR4-stimulated splenocytes and in a mouse model of primary Sjögren’s syndrome." (PMID 34527418, 2021). "Moreover, HMGB1 decreased Aqp5 mRNA levels in a mouse model of Sjögren’s syndrome through the activation of the toll-like receptor 4 (TLR4)/NFkB pathway." (PMID 36768212, 2023). "TLR2, TLR3, and TLR4 were strongly expressed on the SGECs of patients with Sjögren syndrome, and TLR2 signaling induces the production of IL-23/IL-17 via IL-6 and signal transducer and activator of transcription (STAT) in the NF-κB pathway in Sjögren syndrome." (PMID 33224145, 2020).
viral hepatitis (8 papers, 2014 to 2025). An acute or chronic inflammation of the liver parenchyma caused by viruses. "By suppressing high mobility group protein box 1 (HMGB1) cytokine activity and causing TLR4 gene deficit, 18βGA therapy reduced hepatic inflammatory damage in viral hepatitis." (PMID 36903944, 2023). "In the context of viral hepatitis, the gut microbiota plays a critical role in facilitating hepatitis B virus clearance via TLR4 signaling pathways." (PMID 39931363, 2025). "It is well documented that TLR4 expression is increased in livers with viral hepatitis, and its concurrent overexpression with TLR9 was correlated with a poor prognosis in HCC patients." (PMID 38473265, 2024). "Growing evidence supports TLR4’s crucial role in the so-called liver inflammation–fibrosis–carcinoma (IFC) sequence, modulating the inflammatory response in viral hepatitis, autoimmune liver disease, and alcohol-induced liver damage." (PMID 38473265, 2024). "A growing body of clinical studies has shown that TLR4 expression and activation are increased in patients with viral hepatitis-induced HCC and that elevated serum levels of soluble TLR4 may be a useful biomarker for HCC detection and monitoring." (PMID 37896221, 2023).